SCGB2A1 (secretoglobin family 2A member 1)
Description:
May bind androgens and other steroids, may also bind estramustine, a chemotherapeutic agent used for prostate cancer. May be under transcriptional regulation of steroid hormones.
Synonyms: MGB2; UGB3; LPHC; MGC71973; LPNC
Tractability: Antibody: UniProt places it where antibodies can reach, with high confidence; UniProt predicts a signal peptide or a membrane-spanning region; its Gene Ontology location is reachable by antibodies, with medium confidence.
Gene: Protein-coding gene on chromosome 11 (62,208,673 to 62,213,943, forward strand). Ensembl gene ENSG00000124939.
Subcellular location: Secreted
Subcellular location (Human Protein Atlas): Vesicles; Predicted to be secreted
Gene Ontology:
Molecular function: protein binding
Biological process: androgen receptor signaling pathway
Cellular component: extracellular region
Genetic constraint (gnomAD): Loss-of-function variants: 6 observed, 7.44 expected, observed/expected ratio (o/e) 0.81, 90% interval 0.44 to 1.56. That is too few expected variants to judge how well the gene tolerates losing a copy. Missense variants: 133 observed, 108.48 expected, observed/expected ratio (o/e) 1.23, 90% interval 1.06 to 1.42. Synonymous variants: 36 observed, 36.54 expected, observed/expected ratio (o/e) 0.99, 90% interval 0.75 to 1.3.
Homologues: Orthologues: chimpanzee SCGB2A1 (97% identical), macaque SCGB2A1 (86% identical), dog SCGB2A2 (47% identical), pig PHEROC (42% identical), mouse Scgb2a2 (38% identical), rat Scgb2a1 (35% identical), rat Scgb2a1 (32% identical). Paralogues in human: SCGB2A2 (57% identical).
Diseases named in the same sentence as SCGB2A1 in open-access papers:
SCGB2A1 is named in the same sentence as 29 diseases in open-access papers, as found by Europe PMC text mining. Sharing a sentence is not in itself a finding about the gene and the disease. The quoted sentences say what the papers report.
breast cancer (8 papers, 2006 to 2025). A primary or metastatic malignant neoplasm involving the breast. "Mammaglobin B (also called SCGB2A1 or lacryglobin) is overexpressed in breast cancer and serves as a biomarker for axillary lymph node micrometastases in breast cancer patients." (PMID 32992445, 2020).
dry eye (2 papers, 2020 to 2022). "Based on our study, attention should be paid to genes such as LCN1, LTF and SCGB2A1, which had lower expression levels in pterygium, to determine whether they are directly involved in the development of pterygium and dry eye." (PMID 32411530, 2020).
gastric cancer (2 papers, 2011 to 2021). A primary or metastatic malignant neoplasm involving the stomach. "Of these 12 genes, 7 genes highly expressed in gastric cancer tissues were down-regulated (ITGB5, TYMS, MYB, APOC1, CBX5, PLA2G2A, KIF20A) and 5 low-expressed genes were up-regulated after vorinostat treatment (SCGB2A1, TCN1, CFD, APLP1, NQO1." (PMID 21931799, 2011).
pterygium (2 papers, 2020 to 2021). A wedge-shaped fibrovascular lesion arising from the bulbar conjunctiva and extending to the cornea. "An early microarray study also reported downregulation of SCGB2A1 in pterygium." (PMID 34769520, 2021). "From the results of RNA-Seq, LCN1, LTF, SCGB2A1, HBA1 (hemoglobin subunit alpha 1) and HBA2 (hemoglobin subunit alpha 2) ranked as the top five DEGs in the comparison between pterygium and normal tissues." (PMID 32411530, 2020). "The mRNA expressions of SCGB2A1, LTF and LCN1 were significantly decreased in pterygium tissues compared with normal control tissues, while the mRNA levels of HBA1 and HBA2 were higher in the pterygium tissues than in the control tissues." (PMID 32411530, 2020).
colorectal cancer (1 paper, 2024). A primary or metastatic malignant neoplasm that affects the colon or rectum. "In the liver metastatic tissue derived from patients of colorectal cancer, SCGB2A1 was identified as a novel hypoxia‐inducible gene and prognostic marker associated with chemoresistance and radioresistance." (PMID 38013642, 2024).
endometrial cancer (1 paper, 2025). Primary or metastatic malignant neoplasm involving the endometrium (mucous membrane that lines the endometrial cavity). "Additionally, another study identified a a panel of fivegenes (ASRGL1, RHEX, SCGB2A1, SOX17, and STX18) as biomarkers for predicting lymph node metastasis in early-stage endometrial cancer patients." (PMID 39980551, 2025).
lung carcinoma (1 paper, 2011). "The expression of SCGB1D1 (LIPA), SCGB2A1 (MGB2), and SCGB2A2 (MGB1) has been shown to be upregulated in human lung cancers." (PMID 21385388, 2011).
skin cancer (1 paper, 2018). "The vast heterogeneity of the sample collection with respect to diverse factors like platforms, origin, parts of the body, etc. positively influenced in the finding of 6 genes that had not previously related to skin cancer: SCGB2A1, CRYBA2, ANXA3, PCP4, SOSTDC1 and MYO15A." (PMID 29750795, 2018).
tumor (15 papers, 2003 to 2025). "Downregulated were the critical genes CAV1, VWF, and DCN, suggesting loss of tumour-suppressive functions, and upregulated were SCGB2A1, CLDN4, and immune-related genes CCL3 and GZMB, promoting tumour growth and immune evasion." (PMID 41312167, 2025). "SCGB2A1 is highly expressed in some tumor types, and it has been linked to adverse cancer prognosis in others." (PMID 31827514, 2019). "Intriguingly, we observed very low SCGB2A1 expression coupled with a higher frequency of PIK3CA alterations in this tumor group." (PMID 37388735, 2023). "In the TCGA CRC dataset, three genes, ACAA1, CDH19, and SCGB2A1, were downregulated in tumor tissues, whereas the other three genes were overexpressed in tumor tissues." (PMID 35909904, 2022). "Additionally, the genes in the Light-Yellow module include SPDEF, ELAPOR1, C9orf152, PLPP2, and SCGB2A1 and may be involved in several biological processes including tumor immunity and epithelial cell differentiation." (PMID 39596419, 2024). "SCGB2A1, also known as mammaglobin B (MGB-2), is a secretoglobin involved in adenocarcinoma development when the tumor originates in organs such as the ovary and endometrium." (PMID 32039004, 2019). "After that, we re-subtypeed tumor cells, and annotated them according to each cell marker gene, and identified six tumor cell subtypes: C0 XIST+ tumor cells, C1 SCGB2A1+ tumor cells, C2 IGF2+ tumor cells, C3 UBE2C+ tumor cells, C4 TFF3+ tumor cells and C5 IGFBP3+ tumor cells." (PMID 39896800, 2024). "Increased PIK3CA alterations and downregulation of SCGB2A1, the inhibitor of PI3K kinase, in hDNAmad+ tumors, might promote tumor growth/proliferation and stemness." (PMID 37388735, 2023). "The mechanism was reported to involve the SNHG20/miR-6516-5p/secretoglobin family 2A member 1 (SCGB2A1) signalling pathway: SNHG20 suppressed miR-6516-5p level, which negatively modulated SCGB2A1, a positive regulator of tumour cell activity that is elevated in PCa." (PMID 33968736, 2021).
cancer (11 papers, 2003 to 2024). A tumor composed of atypical neoplastic, often pleomorphic cells that invade other tissues. "Eight genes in the signature had reduced expression in the aggressive cancers, and decreased expression of SCGB2A1 is known to be associated with poor survival in EC37,38." (PMID 34873276, 2021). "Following, the mRMR algorithm selected the SCGB2A1 gene as the next with more information to discern among the 7 cancer-related skin states." (PMID 29750795, 2018). "Importantly, Secretoglobin, Family 2A, Member 1 (Scgb2a1) encodes a component of prostatein, a major androgen-binding protein secreted by rat prostate, and hence suggests potential implications for cancer risk and response to chemotherapeutics associated with prostatein binding." (PMID 26973527, 2016). "In addition, as SCGB2A1 is preferably expressed in differentiated endometrial cells and differentiated EC tumors, we examined cancer stem cell phenotype." (PMID 37388735, 2023). "SCGB2A1 appeared as down-expressed for all the cancer-related skin states, but MCC." (PMID 29750795, 2018). "Additionally, its expression adds complementary information to what it is already provided by DSC3 and SCGB2A1, providing a better discernment among the 7 cancer-related skin states." (PMID 29750795, 2018). "Based on the expression profiles of 5 genes, PCA showed that normal and cancer samples were clearly separated, with COMP, ICA1, and PSMB1 contributing to PC1 and ACAA1 and with SCGB2A1 contributing to PC2." (PMID 35909904, 2022). "The expression of PIGR, DEFB1, LTF, CLU, SCGB2A1 and S100A7, while having a positive role in cancer elimination, were either downregulated or not changed in all or some of the BC subtypes." (PMID 38589404, 2024).
SCGB2A1 also shares sentences with these, for which no sentence is quoted: ovarian carcinoma (5 papers); adenocarcinoma (2); bladder (2); adenoma (1); breast tumor (1); carcinosarcoma (1); cervical adenocarcinoma (1); cholangioma (1); endometrioid endometrial carcinomas (1); endometrioid tumor (1); fibrosarcoma (1); glioma (1); gynecological cancers (1); keratoconus (1); liver cancer (1); ovarian adenocarcinoma (1); ovarian tumours (1); Seizure (1); tumors of the esophagus (1).